CPT1A (carnitine palmitoyltransferase 1A)
Diseases named in the same sentence as CPT1A in open-access papers (continued):
Sharing a sentence is not in itself a finding about the gene and the disease.
diabetic nephropathy (2 papers, 2016 to 2024). "This is in accordance with a previous study in which Cpt1a expression was inhibited in diabetic nephropathy, a common aging-associated disease." (PMID 26886165, 2016). "Compared to the strongly positive signal in normal kidneys, CPT1A and PPARα were decreased in kidney biopsies from patients with CKD, including IgAN, membranous nephropathy (MN), lupus nephritis (LN) and diabetic nephropathy (DN)." (PMID 39438470, 2024).
Hypercholesterolemia (2 papers, 2020 to 2023). An increased concentration of cholesterol in the blood. "We also found altered DNA methylation in patients with hypercholesterolemia, in key genes associated with fatty acid transport and metabolism (hypomethylated: PPARD, PPARG, SLC27A1, SLC27A3 and SLC25A20, and hypermethylated: ANGPTL4, ACLS6, ACADM and CPT1A)." (PMID 33028190, 2020).
iron deficiency (2 papers, 2016 to 2020). "The proteome profile identified 4 novel factors to be conversely regulated upon iron deficiency versus iron excess, namely CPT1A, MMP14, XDH, and PYGL." (PMID 33023155, 2020).
ischemic stroke (2 papers, 2025 to 2026). A stroke disorder caused by obstruction of blood flow to the brain, due to thrombotic (local blood clot formation) or embolic (due to a blood clot or other material traveling from another site) event. "Next, we explored the effects of CPT1A dysfunction on glial scar formation and the change of ferroptotic regulators after ischemic stroke." (PMID 41195589, 2026). "CPT1A, the rate-limiting enzyme in mitochondrial FAO, is a pivotal therapeutic target in ischemic stroke due to its role in amplifying neuroinflammation." (PMID 41184254, 2025).
kidney cancer (2 papers, 2020 to 2026). Primary or metastatic malignant neoplasm involving the kidney. "TCGA data analysis revealed that low expression levels of PGC1A and CPT1A in general kidney cancer are associated with poor patient prognosis." (PMID 41716419, 2026). "The survival curve also showed that CPT1A expression is associated with the overall survival of kidney cancer patients." (PMID 33381539, 2020). "The results indicate that the expression of CPT1A in kidney cancer tissue is significantly lower than that in normal kidney tissue." (PMID 33381539, 2020). "The expression of CPT1A in the kidney cancer tissue was significantly lower than that in the normal tissue." (PMID 33381539, 2020). "We performed the CCK-8 assay to determine whether CPT1A can affect the proliferation of kidney cancer cells." (PMID 33381539, 2020). "Similarly, we used a combination of data from the TCGA database and clinical data for evaluating the correlation between the expression of CPT1A and the prognosis of patients in kidney cancer." (PMID 33381539, 2020).
non-alcoholic steatohepatitis (2 papers, 2021 to 2022). "In addition, pirfenidone prevented myocardial steatosis and fibrosis in a mouse model of nonalcoholic steatohepatitis (NASH) by overexpressing PPARα, PPARγ, ACOX1, and CPT1A protein levels and decreasing Timp1, Col I, Col III mRNA levels." (PMID 33809061, 2021).
osteoarthritis (2 papers, 2024 to 2025). A noninflammatory degenerative joint disease occurring chiefly in older persons, characterized by degeneration of the articular cartilage, hypertrophy of bone at the margins and changes in the synovial membrane. "In contrast, in Jiang and colleagues’ study, in a mouse model of osteoarthritis, the pharmacological inhibition of Cpt1a appears to alleviate oxidative damage and chondrocyte senescence by regulating mitochondrial dysfunction and mitophagy." (PMID 39456222, 2024).
ovarian tumor (2 papers, 2009 to 2020). "We found that CPT1A is upregulated in ovarian tumors compared to normal ovaries." (PMID 32312965, 2020). "In recurrent ovarian tumors, CPT1A expression was positively correlated with COL11A1 expression." (PMID 32312965, 2020).
pancreatic cancer (2 papers, 2024 to 2025). "CPT1A knockdown in pancreatic cancer cell lines MIA PaCa-2 and SU.86.86 reduced ATP production by 40-50%." (PMID 40521210, 2025). "The average H-score for CPT1A in normal tissue was 11.3, while that in pancreatic cancer tissue was an average of 35.5, i.e., a 3.14-fold increase in expression compared with that in normal tissue." (PMID 40521210, 2025). "Expression of CPT1A mRNA also increased in patients with pancreatic cancer, as shown by the TCGA data." (PMID 40521210, 2025). "The increase in CPT1A expressions observed in grade 2 and grade 3 pancreatic cancer was statistically significant; indeed, there was an up to 4-fold increase in the H-score between grade 3 cancer and normal tissue." (PMID 40521210, 2025). "Additionally, researchers enhance lipid metabolism in pancreatic cancer cells by increasing the expression of carnitine palmitoyltransferase 1a (CPT1a), acyl-CoA oxidase (AOX), and peroxisome proliferator-activated receptor γ (PPARγ), which helps protect against metabolic stress caused by drugs." (PMID 39609317, 2024). "To investigate the impact of FAO on the development of pancreatic cancer, we compared the expression of CPT1A, a key marker of FAO, by performing immunohistochemical analysis of tissues from patients with pancreatic cancer." (PMID 40521210, 2025).
pancreatic ductal adenocarcinoma (2 papers, 2020 to 2024). An infiltrating adenocarcinoma that arises from the epithelial cells of the pancreas. "We observed a similar depletion of lipid reserves in a C-26 mouse cachexia model; furthermore, the beta-oxidation gene Carnitine Palmitoyltransferase 1A (CPT1A, the mammalian homologue of Whd) is negatively correlated with muscle quality in cachectic patients with pancreatic ductal adenocarcinoma." (PMID 38429578, 2024).
psoriasis (2 papers, 2025 to 2026). An autoimmune condition characterized by red, well-delineated plaques with silvery scales that are usually on the extensor surfaces and scalp. "Subsequent molecular biology experiments demonstrated that brusatol ameliorates psoriasis-associated dyslipidemia by modulating the AMPK-mediated SREBP-1c/FASN and PPARα/CPT1A signaling pathways." (PMID 41508030, 2026).
pulmonary hypertension (2 papers, 2022 to 2025). Increased pressure within the pulmonary circulation due to lung or heart disorder. "This can serve to better guide the development of new therapies that upregulate endothelial Cpt1a or inhibit EndoMT to treat BPD‐associated pulmonary hypertension." (PMID 39799584, 2025). "Therefore, neonatal hyperoxia causes Cpt1a reduction in lung endothelium, which results in EndoMT persistent pulmonary vascular remodeling and pulmonary hypertension." (PMID 39799584, 2025). "We hypothesized that neonatal hyperoxia causes EndoMT by downregulating endothelial Cpt1a, thereby resulting in pulmonary vascular remodeling and pulmonary hypertension." (PMID 39799584, 2025). "Endothelial Cpt1a reduction contributes to, whereas Cpt1a upregulation represses, neonatal hyperoxia‐induced pulmonary vascular remodeling and pulmonary hypertension." (PMID 39799584, 2025). "Therapeutic upregulation of Cpt1a inhibits neonatal hyperoxia‐induced pulmonary vascular remodeling and right ventricular hypertrophy as well as pulmonary hypertension." (PMID 39799584, 2025). "Altogether, we show that endothelial Cpt1a deletion contributes to neonatal hyperoxia‐induced pulmonary vascular and right ventricular remodeling as well as pulmonary hypertension." (PMID 39799584, 2025). "Altogether, these results suggest that endothelial Cpt1a deletion contributes to neonatal hyperoxia‐induced pulmonary vascular and right ventricular remodeling as well as pulmonary hypertension by upregulating EndoMT." (PMID 39799584, 2025). "Endothelial Cpt1a deletion further increases, whereas nanoparticle‐mediated endothelial Cpt1a gene delivery inhibits pulmonary vascular remodeling and pulmonary hypertension in this mouse model." (PMID 39799584, 2025). "Altogether, therapeutic upregulation of Cpt1a expression inhibits neonatal hyperoxia‐induced pulmonary vascular and right ventricular remodeling as well as pulmonary hypertension." (PMID 39799584, 2025). "To further determine the role of endothelial Cpt1a in modulating neonatal hyperoxia‐induced pulmonary hypertension, we evaluated pulmonary arterial wall thickness in vessels with an outer diameter <100 μm in EC‐specific Cpt1a KO mice and their WT littermates exposed to hyperoxia as neonates." (PMID 39799584, 2025). "Whether upregulating Cpt1a attenuates neonatal hyperoxia-induced pulmonary vascular remodeling and pulmonary hypertension remains to be investigated." (PMID 35964084, 2022). "Finally, therapeutic upregulation of Cpt1a using pharmacological treatments and nanoparticle‐mediated endothelial gene delivery as well as blockage of EndoMT were employed to determine their effects on neonatal hyperoxia‐induced pulmonary vascular remodeling and pulmonary hypertension." (PMID 39799584, 2025).
squamous cell carcinoma (2 papers, 2016 to 2025). A carcinoma arising from squamous epithelial cells. "Potential tumor suppressor genes, also found in other squamous cell carcinomas, have been discovered in the lost regions 2q33-q37.3 (PLCD4), 3p26.3-q11.1 (RBMS3, PLCD1, and CACNA2D3) and 11q12.2-q25 (CPT1A, CCND1, FGF4/FGF3, and PPP2R1B)." (PMID 26901676, 2016).
thyroid cancer (2 papers, 2021 to 2023). "Some studies found that LPL, FATP2, and CPT1A can all promote the migration of thyroid cancer cells, while USF-2 inhibits the proliferation of normal thyroid cells and thyroid cancer cells." (PMID 38189054, 2023). "Together, LPL, FATP2 and CPT1A activate fatty acid metabolism to promote thyroid cancer progression." (PMID 34976793, 2021). "In order to verify that LPL, FATP2 and CPT1A involve in metastasis of thyroid cancer, these genes were overexpressed in BHP10-3 cells." (PMID 34976793, 2021). "In addition, ectopic overexpression of LPL, FATP2 and CPT1A can each promote the migration of thyroid cancer cells." (PMID 34976793, 2021). "FATP2 and CPT1A were the significantly elevated protein in thyroid cancer specimens." (PMID 34976793, 2021). "Thus far, CPT1A could be a suitable therapeutic target for thyroid cancer." (PMID 34976793, 2021).
Ureteral obstruction (2 papers, 2024 to 2025). Obstruction of the flow of urine through the ureter. "To define the role of tubular CPT1A in aging and injury, we generated mice with tubule-specific deletion of Cpt1a (Cpt1aCKO mice), and the mice were either aged for 2 years or injured by aristolochic acid or unilateral ureteral obstruction." (PMID 38516886, 2024). "To address this question, we selectively deleted Cpt1a in renal tubules using the inducible Pax8-rTTA;tetO-Cre mice and either aged the mice for 2 years or subjected them to the unilateral ureteral obstruction (UUO) or aristolochic acid nephropathy (AAN) chronic kidney injury models." (PMID 38516886, 2024).
acute biliary pancreatitis (1 paper, 2025). "However, the role of CPT1A in severe acute pancreatitis (SAP) and its underlying mechanisms remain unclear." (PMID 40718711, 2025). "In conclusion, these results suggest that LC pretreatment increases CPT1A expression in mice, providing a significant protective effect against acute biliary pancreatitis." (PMID 40718711, 2025).
Acute hepatic failure (1 paper, 2022). Hepatic failure refers to the inability of the liver to perform its normal synthetic and metabolic functions, which can result in coagulopathy and alteration in the mental status of a previously healthy individual. "The severe phenotype of hypoketotic hypoglycaemia with acute hepatic failure associated with CPT1A deficiency is well described." (PMID 35822099, 2022).
acute kidney injury (1 paper, 2023). Sudden and sustained deterioration of the kidney function characterized by decreased glomerular filtration rate, increased serum creatinine or oliguria. "Their up-regulation can enhance CPT1A expression, consequently improving mitochondrial FAO and ameliorating acute kidney injury." (PMID 38054182, 2023).
acute leukemia (1 paper, 2020). A clonal (malignant) hematopoietic disorder with an acute onset, affecting the bone marrow and the peripheral blood. "The expression of CPT1A was significantly upregulated in acute leukemia cells." (PMID 33381539, 2020).
acute liver failure (1 paper, 2017). Rapid deterioration of liver function causing encephalopathy and coagulopathy. "Presenting with acute liver failure during an episode of acute viral gastroenteritis is characteristic of CPT1A deficiency." (PMID 28748224, 2017).
acute lymphoblastic leukemia (1 paper, 2022). Leukemia with an acute onset, characterized by the presence of lymphoblasts in the bone marrow and the peripheral blood. "Elevated levels of CPT1A are associated with poor prognosis in acute lymphoblastic leukemia." (PMID 35831624, 2022). "CPT1A (the liver isoform) is upregulated in high-grade serous ovarian cancer (HGSOC) and in acute lymphoblastic leukemia, and correlates to poor overall survival." (PMID 35831624, 2022).
adenoma (1 paper, 2024). A neoplasm arising from the epithelium. "Some MP-RNAs (ARID4B, CPT1A, PHKB) had increased number of partners in adenoma samples than in the paracancer samples but decreased in cancer samples." (PMID 38773399, 2024).
Anxiety (1 paper, 2024). Intense feelings of nervousness, tension, or panic often arise in response to interpersonal stresses. "Both adult and aged Cpt1a KO mice showed enhanced exploratory capacity without alterations in anxiety and emotional behavior, as analyzed by the percentage of time that mouse was in the open arms of the EPM structure and the number of grooms." (PMID 37994388, 2024). "Notably, adult and aged Cpt1a KO male mice displayed improved physical activity without changes in anxiety‐related behavior." (PMID 37994388, 2024). "The results obtained from adult and aged Cpt1a KO male mice in the OFT and EPMT exhibited the same pattern of behavior as control mice, suggesting that the differences in physical activity were not related to anxiety." (PMID 37994388, 2024).
aortic valve disease (1 paper, 2016). "Notably, only ACADM, FABP3, ECH1, ACAA2, EHHADH, CPT1A and PLTP of the PPAR pathway were significantly differentially expressed in the MR patients compared to patients with aortic valve disease and normal controls." (PMID 27250500, 2016). "Notably, seven genes (ACADM, FABP3, ECH1, ACAA2, EHHADH, CPT1A and PLTP) of the PPAR signaling pathway were differentially expressed in the left atria of MR patients compared to patients with aortic valve disease and normal controls." (PMID 27250500, 2016). "Notably, only ACADM, FABP3, ECH1, ACAA2, EHHADH, CPT1A and PLTP of the PPAR signaling pathway were differentially expressed in the left atria of MR patients compared to patients with aortic valve disease and normal controls." (PMID 27250500, 2016).
asbestosis (1 paper, 2025). A lung disorder caused by inhalation of asbestos fibers. "CPT1A was also significantly increased in asbestosis compared with healthy participants, suggesting metabolic reprogramming to FAO occurs in lung macrophages during asbestosis." (PMID 40208691, 2025).
Autoimmunity (1 paper, 2025). The occurrence of an immune reaction against the organism's own cells or tissues. "Although fatty acid oxidation is frequently linked to immune tolerance, its disruption like CPT1A inhibition in mice or mutations in humans led to reduced neural autoimmunity, similar to our findings with HF." (PMID 40150860, 2025).
B-cell lymphomas (1 paper, 2020). "Supporting this premise, this subset of B-cell lymphomas expressed high levels of CPT1-A, the isoform needing higher malonyl-CoA concentrations to be inhibited." (PMID 33291682, 2020). "However, it is unclear how FAO-dependent B-cell lymphomas show a preferential expression of CPT1-A and whether some post-translational mechanisms could explain FAO preference." (PMID 33291682, 2020). "The subset of B-cell lymphomas and leukemias that use FAO to proliferate express CPT1-A: the isoform with lower sensitivity to malonyl-CoA and found in Randle-cycle abiding and lipogenic tissues, such as liver." (PMID 33291682, 2020).
bacterial pneumonia (1 paper, 2022). Acute infection of the lung parenchyma caused by bacteria (e.g., Streptococcus pneumoniae, Haemophilus influenzae, Chlamydia pneumoniae, Mycoplasma pneumoniae, and Legionella pneumophila). "Pharmacologic inhibition of Cpt1a increases mortality and impairs control of the infection in a murine model of bacterial pneumonia." (PMID 36513703, 2022).
Barrett’s oesophagus (1 paper, 2024). "Palmitate upregulated carnitine palmitoyltransferase 1A (CPT1A) in the disease sequence from Barrett’s oesophagus to OAC, in both in vitro and mouse models, resulting in increased cell proliferation." (PMID 38248845, 2024).
bladder tumors (1 paper, 2021). "Although high expression of CPT1A significantly correlated with poor patients’ survival, CPT1B transcripts have been reported to be downregulated in high grade bladder tumors and positively associated with patients’ survival." (PMID 34764423, 2021).
CACT deficiency (1 paper, 2022). "CPT1 deficiency (CPT1D), CPT2 deficiency (CPT2D), and CACT deficiency (CACTD) are rare autosomal inherited recessive disorders, and the causative genes are CPT1A, CPT2, and SLC25A20, respectively." (PMID 35360862, 2022).
cardiomyopathy (1 paper, 2018). A disease of the heart muscle or myocardium proper. "In 8 patients with symptomatic presentation, FAODs manifested as LCHAD/MTP deficiencies by recurrent rhabdomyolysis or cadiomyopathy (6 patients), and VLCAD deficiency by cardiomyopathy (1 patient), and CPT1A deficiency by hepatic failure (1 patient)." (PMID 29519241, 2018). "Two patients with LCHAD/MTP deficiencies died due to severe cardiomyopathy in the neonatal period, and developmental disability was noted in CPT1A deficiency (1 patient)." (PMID 29519241, 2018).
carnitine deficiency (1 paper, 2018). "In our current study, a fair outcome was observed in the patients with MCAD, CPT1A or primary carnitine deficiency identified by newborn screening." (PMID 29519241, 2018). "L-carnitine was given to 5 patients with MCAD deficiency even though the carnitine levels were within normal range, 1 patient with primary carnitine deficiency, and 1 patient with CPT1A deficiency." (PMID 29519241, 2018). "The remaining 2 patients with VLCAD deficiency and all patients with MCAD deficiency, SCAD deficiency, primary carnitine deficiency, or CPT1A deficiency were free of a metabolic crisis during the follow-up period." (PMID 29519241, 2018). "FAODs were identified in 14 patients by newborn screening: VLCAD deficiency (5 patients), MCAD deficiency (5 patients), primary carnitine deficiency (1 patient), CPT1A deficiency (1 patient), LCHAD/MTP deficiencies (1 patient), and SCAD deficiency (1 patient)." (PMID 29519241, 2018). "Alternatively, other FAODs, including primary carnitine deficiency, CPT1A or SCAD deficiencies, were identified in a small number of patients." (PMID 29519241, 2018).
cataract (1 paper, 2025). Partial or complete opacity of the crystalline lens of one or both eyes that decreases visual acuity and eventually results in blindness. "In conclusion, we have identified variants in the CPT1A gene that are strongly associated with hereditary cataracts in the Siberian Husky, Samoyed, Icelandic Sheepdog and Norwegian Buhund breeds of domestic dog." (PMID 40184359, 2025). "However, further work is needed to elucidate the pathophysiology underlying the association between CPT1A and cataracts in Northern breeds." (PMID 40184359, 2025). "The association between cataracts and the CPT1A gene is intriguing and has not previously been reported for any species." (PMID 40184359, 2025).